GNMT (glycine N-methyltransferase)
Diseases named in the same sentence as GNMT in open-access papers (continued):
Sharing a sentence is not in itself a finding about the gene and the disease.
colorectal cancer (1 paper, 2014). A primary or metastatic malignant neoplasm that affects the colon or rectum. "Moreover, sarcosine levels and GNMT expression were also increased in tissue and feces of experimental azoxymethane-induced colorectal cancer." (PMID 24884785, 2014).
congenital heart defects (1 paper, 2021). "Furthermore, genetic variants of SHMT1, BHMT, MGST1, MGMT, MTHFS, GNMT, and TRDMT1 were associated with an increased risk of congenital heart defects after prenatal antidepressant exposure." (PMID 33981330, 2021).
diabetic nephropathy (1 paper, 2020). "At the same time, it is urgent to explore whether GNMT can be used as a potential therapeutic target in diabetic nephropathy." (PMID 33241846, 2020). "However, whether GNMT can regulate fibrosis and inflammatory response in diabetic nephropathy has not been reported." (PMID 33241846, 2020).
gallbladder cancer (1 paper, 2021). "GNMT (Glycine N-Methyltransferase) catalyzes the methylation of glycine to form sarcosine, but in this study, we found that it mainly participates in bile metabolism and has little to do with the methylation of hub genes in the development of gallbladder cancer." (PMID 33718182, 2021).
gastric cancer (1 paper, 2015). A primary or metastatic malignant neoplasm involving the stomach. "RASSF1A, p14ARF, and MGMT; CHRNA3, DOK1, and GNMT; p16, hMLH1, MINT1, MINT2, MINT12, MINT25, and MINT31; APC, CDH1, MHL1, CDKN2A, CDKN2B, and RUNX3; CDH1; DKK3; PTEN; MGMT; TFPI2; CACNA2D3; PCDH10; SOX2; MAL; and COX2 were previously reported to be hypermethylated in gastric cancer." (PMID 26121593, 2015).
Hepatitis (1 paper, 2021). Inflammation of the liver. "However, in glycine N-methyltransferase- (GNMT-) deficient mice that can spontaneously develop nonalcoholic steatohepatitis (NASH), inhibition of NK cells can ameliorate Con A-induced hepatitis." (PMID 33506011, 2021).
hydronephrosis (1 paper, 2023). Collection of urine in the renal pelvis that results in dilatation of the renal pelvis and calyces. "Furthermore, UUO significantly increased the expression of GNMT in mice; in addition, it caused renal injury as well as the development of both hydronephrosis and tubular injury." (PMID 37047834, 2023). "First, we examined the expression of GNMT not only in kidney specimens from patients with hydronephrosis but also in UUO mice." (PMID 37047834, 2023). "Our human data first demonstrated that the expression of GNMT is increased in subjects with hydronephrosis, and an in vivo study also showed increased expression of GNMT after UUO surgery." (PMID 37047834, 2023). "We found that treatment with folic acid decreased UUO-induced hydronephrosis in WT mice, while deletion of GNMT exacerbated UUO-induced hydronephrosis." (PMID 37047834, 2023). "We found that the expression of GNMT in immunohistochemical staining was increased in the hydronephrosis group compared with the control group." (PMID 37047834, 2023).
memory impairment (1 paper, 2021). "GNMT expression has been detected in the hippocampus and its deficiency results in reduced neurogenic capacity, spatial learning, and memory impairment." (PMID 33804025, 2021).
metastatic prostate carcinoma (1 paper, 2014). A carcinoma that arises from the prostate gland and has spread to other anatomic sites. "It was recently reported that sarcosine, which is regulated by GNMT, increased markedly in metastatic prostate cancer." (PMID 24800880, 2014).
ovarian carcinoma (1 paper, 2025). A malignant neoplasm originating from the surface ovarian epithelium. "For instance, systematic comparisons between HCC and NNMT-high malignancies (e.g., breast and ovarian cancers) could delineate conserved pathways (e.g., NAD+ salvage mechanisms) versus liver-specific vulnerabilities, such as the GNMT–NNMT regulatory axis in methionine cycle homeostasis." (PMID 40427612, 2025).
peroxisome biogenesis disorder 4B (1 paper, 2024). Any peroxisome biogenesis disorder due to PEX6 defect characterized by the association of early-onset cerebellar ataxia with hearing loss and blindness. "Diseases associated with GNMT include GNMT deficiency and peroxisome biogenesis disorder 4B." (PMID 39062651, 2024).
psoriasis (1 paper, 2021). An autoimmune condition characterized by red, well-delineated plaques with silvery scales that are usually on the extensor surfaces and scalp. "Based on the sequencing results, the genes of CBS, Sardh, GNMT, Pgam2, and Sdsl in the Gly-Ser-Thr axis were selected for the determination of protein concentrations on day 12 to explore the involvement of this metabolic pathway in the TDG treatment of psoriasis." (PMID 33995034, 2021).
renal fibrosis (1 paper, 2023). A final common manifestation of a wide variety of chronic kidney diseases characterized by glomerulosclerosis and tubulointerstitial fibrosis. "Given this, it is crucial to identify potential GNMT-inducers for prevention or treatment of renal fibrosis in the future." (PMID 37047834, 2023). "Second, this study highlights the involvement of GNMT in the folic acid-related mechanisms relevant to renal fibrosis." (PMID 37047834, 2023). "We propose a novel role for folic acid in the treatment of renal fibrosis, which indicates that GNMT may be a therapeutic target." (PMID 37047834, 2023). "Therefore, we conclude that GNMT may be a therapeutic target for renal fibrosis, and that folic acid may be used as a treatment." (PMID 37047834, 2023). "However, as yet neither the therapeutic effects of folic acid in renal fibrosis nor whether GNMT is involved in these folic acid-associated mechanisms has been investigated." (PMID 37047834, 2023). "Secondly, while the study sheds light on the effects of folic acid and GNMT on renal fibrosis, it does not suggest a detailed mechanism for how they interact to produce these effects." (PMID 37047834, 2023).
sarcoma (1 paper, 2017). A usually aggressive malignant neoplasm of the soft tissue or bone. "Nonetheless, these findings also cannot exclude the possibility that GNMT deficient liver progenitor/stem cells are more susceptible for transdifferentiation into sarcoma-like cells; and further investigation is needed to evaluate the role of GNMT in this transdifferentiation." (PMID 28596515, 2017).
Type 1 diabetes (1 paper, 2020). "Current results suggest that carnosine may exert anti-inflammatory and antifibrotic effects in STZ-induced Type 1 diabetes experimental mouse models by targeting GNMT." (PMID 33241846, 2020). "Additionally, the decreased mRNA level of GNMT in Type 1 diabetes mice was markedly reversed by carnosine treatment." (PMID 33241846, 2020).
Ureteral obstruction (1 paper, 2023). Obstruction of the flow of urine through the ureter. "Later, wild-type and GNMT knockout (GNMT−/−) mice were subjected to unilateral ureteral obstruction (UUO) and then treated with either folic acid or vehicle for 14 days." (PMID 37047834, 2023).
viral hepatitis (1 paper, 2018). An acute or chronic inflammation of the liver parenchyma caused by viruses. "To investigate whether the relationship between GNMT and miR-224 is correlated with viral hepatitis, we extended the analysis to 78 pairs of HCC tumor and tumor-adjacent tissues from TLCN." (PMID 30115977, 2018).
tumor (49 papers, 2013 to 2026). "Considering that AurA inhibition enhanced GNMT expression in BMDMs in our experiment, we detected GNMT expression in tumor-associated macrophages (TAMs)." (PMID 40920087, 2025). "The results of the present study in conjunction with the histopathological evaluation of the liver of mice demonstrate that apigenin does not lead to the development of neoplasia; in fact, the risk of neoplasia is reduced by high expression of GNMT." (PMID 40415790, 2025). "Loss of GNMT tumor suppressor function results in unchecked activation of the mTOR signaling pathway, promoting HCC cell proliferation, motility, and tumor invasion." (PMID 41465470, 2025). "Our previous studies gave underlying mechanisms by which GNMT can participate in tumor prevention/suppression in humans." (PMID 34065390, 2021). "One of the candidate tumor-suppressor genes that we uncovered more recently was GNMT, a methyltransferase that is associated with the methylation potential of the cell." (PMID 33802396, 2021). "Glycine N-methyltransferase (GNMT) encodes a tumour suppressor gene recently associated with T cell immune response." (PMID 32183058, 2020). "This is an epigenetic mechanism for loss of function of tumor suppressors and our study here confirmed the downregulation of GNMT expression." (PMID 31277598, 2019). "In this study, livers of Gnmt−/− mice at the age of 4 months developed chronic steatohepatitis and tumor-associated signaling pathways stimulated by GNMT deficiency were initiated." (PMID 30217986, 2018). "The phenomenon that AAV8-GNMT inhibited liver inflammation and tumor growth in Gnmt−/− mice suggested therapeutic potential of AAV8-GNMT in such patients with congenital GNMT deficiencies." (PMID 30217986, 2018). "Subsequently, we used genotypic analysis to show that the rates of loss of heterozygosity at the GNMT locus in paired tumor and tumor-adjacent tissues from HCC patients were 36 to 47%5." (PMID 30115977, 2018). "Previously, we identified GNMT (glycine N-methyltransferase) as a tumour susceptibility gene and characterized its promoter region." (PMID 23883094, 2013). "In contrast to these enzymes, in our study cancer tissues and tumor-derived cell lines demonstrated the total loss of GNMT." (PMID 23936142, 2013). "Third, loss of AAV8-mediated GNMT expression may occur during the tumor formation in the livers of Gnmt−/− mice." (PMID 30217986, 2018). "Thus, it is expected that the sarcosine amount is highly dependent on the action of GNMT, which is encoded by tumor-susceptible gene GNMT." (PMID 26999116, 2016). "The expression patterns of COLEC10, KMO, and GNMT in LIHC were correlated with tumor staging (P(NF) < 0.05)." (PMID 40026364, 2025). "Inhibits GNMT, abolishing its tumor suppressor function by ceasing to inhibit the mTOR pathway, leading to cell proliferation." (PMID 41465470, 2025). "(F) Co-immunofluorescence staining of DAPI, F4/80, and glycine N-methyltransferase (GNMT) in tumor section from A; Scale bars: 20 μm." (PMID 40920087, 2025). "The expression levels of COLEC10, KMO, and GNMT were observed to be markedly reduced in tumor tissues compared to matched normal counterparts (P < 0.05)." (PMID 40026364, 2025). "Studies have shown that GNMT is a tumor suppressor gene and its expression is downregulated in tumor tissue." (PMID 40920087, 2025). "GNMT is a tumor suppressor for HCC because it protects the cells from the cytotoxicity induced by carcinogens." (PMID 37375411, 2023). "The activation of GNMT expression by androgens would be consistent with a tumor-promoting role, whereas the inhibition by the MYC and PI3K pathways would argue in the opposite direction." (PMID 35197445, 2022).
tumor (continued). "Of the remaining 41 genes, three (PIGC, PKM and PPIB) were commonly upregulated with oncogenic potential and 31 were commonly downregulated among CP and PDAC-CP, of which, 3 (AZGP1, EGLN1 and GNMT) were tumour suppressors." (PMID 35854233, 2022). "Data from GEPIA demonstrated MAT1A and GNMT expressions were significantly higher in the adjacent normal tissues (n = 160) than those in the HCC tumor tissues (n = 369) (p < 0.001)." (PMID 35008908, 2022). "The loss of GNMT produces an increase of SAM levels that induces aberrant DNA and histones methylation, causing alterations in epigenetic regulation that results in tumor progression in mice liver." (PMID 36144184, 2022). "In this paper, we examined the status of GNMT, a gene identified in our previous studies as a putative tumor-suppressor gene and biomarker for PC." (PMID 33802396, 2021). "Further, we show that PGG upregulates GNMT expression in a PC cell line, suggesting a role for GNMT as a tumor suppressor." (PMID 33802396, 2021). "Taken together, our results strongly suggest that GNMT is a tumor-suppressor gene in PC, with potential to act as a diagnostic and prognostic biomarker." (PMID 33802396, 2021). "A significant inverse correlation between miR-224 and GNMT expression was seen in HBx transgenic mice liver and tumor (R = −0.477, P = 0.016), which was consistent with the clinical findings in HBV-related HCC specimens." (PMID 30115977, 2018). "A recent study identified a novel tumorigenic mechanism of dysregulation of phosphatidylinositol 3,4,5-trisphosphate-dependent Rac exchanger 2 protein (PREX2) expression in a tumor environment where GNMT expression is inhibited." (PMID 29416626, 2018). "Consistent with the in vitro findings, the enhanced tumor sizes by miR-224 were attenuated by GNMT expression in the GNMT/miR-224 group." (PMID 30115977, 2018). "The levels of miR-224 and GNMT mRNA showed a significant inverse relationship in tumor specimens from HCC patients." (PMID 30115977, 2018). "Consistent with previous reports, the expression levels of miR-224, miR-491 and miR-93* were up-regulated in HCC while GNMT was down-regulated in tumor tissues from 10 HCC patients." (PMID 30115977, 2018). "Another example of tumour specific ablation of proteins refers to glycine N-methyltransferase (GNMT)." (PMID 25872475, 2015). "GNMT is known to play a role in the maintenance of genetic stability, and a novel tumour suppressor function was recently reported that is independent of its catalytic activity but does require its nuclear localization." (PMID 25872475, 2015). "Surprisingly, our finding is in disagreement with two recently published studies, which demonstrated that GNMT has a promoting effect on cancer cell proliferation and that knockdown of the enzyme by RNA interference induces apoptosis and inhibits tumor growth." (PMID 23936142, 2013). "In addition, in vitro and xenograft approaches provided support for a positive role of GNMT in the regulation of specific PCa features, despite the fact that some studies raised controversy around its potential tumor-suppressive nature." (PMID 35197445, 2022). "Importantly, we were also able to show that GNMT is downregulated by 100-fold or more in approximately half of the high-quality early-stage paired tumor tissue samples obtained from the University of Iowa Tissue Procurement Core Facility." (PMID 33802396, 2021). "GNMT has been proposed to be a novel tumor suppressor in cellular defense against DNA damage." (PMID 34065390, 2021). "In addition, SMAD family member 4 (Smad4) and glycine-N-methyltransferase (GNMT) were described among miR-224 target genes, and their involvement in liver injury and tumor progression was proved by in vitro and in vivo models." (PMID 31805631, 2019). "Glycine N-methyltransferase (GNMT) is a tumor suppressor for HCC." (PMID 30115977, 2018).
tumor (continued). "HBV-related HCC specimens, HBx transgenic mouse model and and miR-224 overexpression enhanced and GNMT overexpression reduced tumor growth in vivo, which is consistent with the in vitro data, In addition, AAV-GNMT reduced CCl4-induced miR-224 expression and fibrosis formation in mouse liver." (PMID 30115977, 2018). "It is reported that GNMT, the most abundant methyltransferase in the liver, has tumor suppressor function and is associated with nonalcoholic fatty liver disease (NAFLD) which accompanies hepatic methionine deficiency and homocysteine elevation." (PMID 30138348, 2018). "Furthermore, GNMT was expressed abundantly in mouse liver tissue but diminished tumor tissues from AFB1-treated wild-type mice." (PMID 30115977, 2018). "miR-224 counteracts the effects of GNMT on the reduction of cell proliferation and tumor growth." (PMID 30115977, 2018). "Therefore, miR-224 plays a tumor-promoting role in colony formation in vitro and tumorigenesis of Huh7 cells in vivo by targeting GNMT." (PMID 30115977, 2018). "Finally, qPCR and immunoblot analysis of tumor samples revealed that GNMT was induced in the PGG-treated group." (PMID 27153064, 2016). "Glycine N-methyltransferase (GNMT) possesses a tumor suppressive effect against HCC." (PMID 27153064, 2016). "Notably, GNMT was downregulated in the tumor tissues collected from patients with HCC." (PMID 37375411, 2023). "In addition, 3 tumour suppressors genes were down regulated: GNMT, AZGP1 and EGLN1." (PMID 35854233, 2022). "During tumor formation in GNMT deficient mice, GNMT acted as a negative regulator in the mitogen-activated protein kinase (MAPK), wingless-type MMTV integration site (Wnt) and Janus kinase and signal transducer and activator of transcription (JAK-STAT) signaling pathways." (PMID 30217986, 2018). "Low expression of MAT1A and GNMT1 were confirmed in the tumor tissues as compared to those in the adjacent normal tissues (for MAT1A and GNMT, p < 0.0001 and p = 0.012, respectively, consistent with the results obtained from the web server." (PMID 35008908, 2022). "Glycine N-methyltransferase (GNMT) is an important cellular enzyme regulating S-adenosylmethionine (SAM) metabolism, as well as a tumor suppressor gene for HCC." (PMID 36077467, 2022). "The GNMT and MAT1A proteins were found exclusively in the cytoplasmic fraction of tumor and normal tissues." (PMID 34065390, 2021). "PNLIPRP1 and GNMT have been documented as the tumor suppressor genes of PC and PHGDH been certified as the tumor promoter gene of PC." (PMID 31706267, 2019). "Glycine N-methyltransferase (GNMT) is abundantly expressed in normal livers and plays a protective role against tumor formation." (PMID 30217986, 2018). "Expectedly, the expression of GNMT was significantly lower and that of miR-224 was significantly higher in HCC tumor tissues than in the tumor-adjacent tissues." (PMID 30115977, 2018). "A distinct inverse gene expression pattern of GNMT and miR-224 was evident in the tumor tissues of 78 pair of HCC samples than in the tumor adjacent tissues." (PMID 30115977, 2018). "It has been shown that restoration of GNMT in HCC cell lines results in repression of cell proliferation and tumor growth." (PMID 27153064, 2016). "Similar to tumor tissues, GNMT was not detectable at the protein level in several human cancer cell lines (data not shown)." (PMID 23936142, 2013). "The enzymes involved in this pathway, including glycine N-methyltransferase (GNMT), S-adenosylhomocysteine hydrolase (SAHH), cystathionine β-synthase (CBS), and cystathionine gamma-lyase (CTH), sensitize cancer cells to ferroptosis and slow down tumor progression." (PMID 41323780, 2025). "However, the downregulation of ASNS, ACAT1, and GNMT expression had no significant impact on tumor invasion." (PMID 37511510, 2023). "Besides, glycine N-methyltransferase (GNMT) catalyzes the methylation of glycine to form sarcosine, which might decrease glycine concentration in the tumor." (PMID 36467068, 2022).
tumor (continued). "However, compared to GFP overexpressed control Ymac-1 cells, neither the cell/tumor morphologies nor the expression profile of EMT/CSC markers were changed in GNMT overexpression Ymac-1 cell (data not shown)." (PMID 28596515, 2017).